ENSG00000252762
Gene: Small nucleolar RNA gene on chromosome 4 (81,928,313 to 81,928,439, forward strand). Ensembl gene ENSG00000252762.
Homologues: Orthologues: mouse Gm56119 (69% identical). Paralogues in human: SNORA31B (80% identical), SNORA31 (62% identical).